ENSG00000253028
Synonyms: LOC124900240
Gene: Small nucleolar RNA gene on chromosome 7 (52,269,437 to 52,269,569, reverse strand). Ensembl gene ENSG00000253028.
Gene Ontology:
Biological process: RNA processing
Cellular component: nucleolus
Homologues: Orthologues: rat LOC120098359 (36% identical). Paralogues in human: SNORA31B (76% identical), SNORA31 (55% identical).